DHDH (dihydrodiol dehydrogenase)
Description:
Catalyzes the NADP(+)-linked oxidation of trans-dihydrodiols of aromatic hydrocarbons to the corresponding catechols. It also catalyzes the oxidation of several pentoses and hexoses. In the reverse reaction in the presence of NADPH, it acts as NADPH-linked reductase on a broad range of substrates including aldehydes, chetones, and alpha-dicarbonyl compounds such as 3-deoxyglucosone, camphorquinone and methylglyoxal.
Synonyms: 2DD; HUM2DD
Tractability: No criterion of Open Targets' tractability assessment is met for any kind of drug.
Gene: Protein-coding gene on chromosome 19 (48,933,699 to 48,944,969, forward strand). Ensembl gene ENSG00000104808.
Subcellular location (Human Protein Atlas): Actin filaments; Nucleoplasm
Gene Ontology:
Molecular function: D-xylose 1-dehydrogenase (NADP+) activity; galactose 1-dehydrogenase (NADP+) activity; glucose 1-dehydrogenase [NAD(P)+] activity; ribose 1-dehydrogenase (NADP+) activity; glucose 1-dehydrogenase (NADP+) activity; nucleotide binding; trans-1,2-dihydrobenzene-1,2-diol dehydrogenase activity
Biological process: D-xylose catabolic process
Genetic constraint (gnomAD): Loss-of-function variants: 29 observed, 31.01 expected, observed/expected ratio (o/e) 0.94, 90% interval 0.69 to 1.27. The upper end of that interval is the gene's LOEUF score, 1.27, which puts it in group 5 of 6, group 1 being the genes least tolerant of losing a copy. Missense variants: 431 observed, 446.13 expected, observed/expected ratio (o/e) 0.97, 90% interval 0.89 to 1.05. Synonymous variants: 201 observed, 189.38 expected, observed/expected ratio (o/e) 1.06, 90% interval 0.94 to 1.19.
Homologues: Orthologues: chimpanzee DHDH (97% identical), dog DHDH (87% identical), macaque DHDH (86% identical), pig DHDH (84% identical), rabbit DHDH (82% identical), mouse Dhdh (79% identical), rat Dhdh (78% identical), guinea pig DHDH (75% identical), tropical clawed frog dhdh (54% identical), tropical clawed frog dhdhl (51% identical), zebrafish dhdh.2 (51% identical), zebrafish dhdh.1 (46% identical), and 3 more. Paralogues in human: GFOD2 (19% identical), GFOD1 (19% identical), BLVRA (16% identical).
Diseases named in the same sentence as DHDH in open-access papers:
DHDH is named in the same sentence as 9 diseases in open-access papers, as found by Europe PMC text mining. Sharing a sentence is not in itself a finding about the gene and the disease. The quoted sentences say what the papers report.
hepatocellular carcinoma (2 papers, 2022 to 2026). A malignant tumor that arises from hepatocytes. "DHDH had been reported to be included in a metabolism-related prognostic signature for hepatocellular carcinoma." (PMID 35615380, 2022).
lung carcinoma (2 papers, 2018 to 2022). "The orthologues were related to DHDH, ATP8B3, and P2RY1 genes, expressed in the lipid membrane, and directly related to skin and lung cancer genes (APP and APPBP2), suggesting that they may share mechanisms among these diseases." (PMID 36542226, 2022).
diabetes (1 paper, 2022). "DHDH is involved in the detoxication of trans-dihydrodiol and carcinogenic metabolites of polycyclic aromatic hydrocarbons; SUCNR1 is related to conditions such as hypertension, diabetes, and obesity, whereas ATP8B3 is involved in aminophospholipid transport in the liver." (PMID 36542226, 2022).
liver cancer (1 paper, 2024). An epithelial or non-epithelial malignant neoplasm that arises from the liver. "Among these, six genes were significantly differentially expressed between liver cancer tissue and adjacent normal tissue (CSAD, SLC16A11, LILRA2, IMMP2L, GLP2R, and DHDH)." (PMID 38927691, 2024).
tumour (2 papers, 2015 to 2025). "Likewise, we observed repressed expression of dihydrodiol dehydrogenase in tumours." (PMID 25872475, 2015). "Furthermore, pathways involved in xenobiotic metabolism (GSTs, DHDH, AKR7A2, HSD11B1L, CYP1B1, UGTs), drug metabolism, nucleotide metabolism, and homologous recombination (RAD51) reflect the tumour’s ability to adapt to environmental stressors and resist therapy." (PMID 41007296, 2025).
cancer (1 paper, 2024). A tumor composed of atypical neoplastic, often pleomorphic cells that invade other tissues. "Elevated DHDH expression in cancer has been correlated with unfavorable prognostic outcome." (PMID 39654885, 2024). "Increased DHDH expression in cancer has been correlated with an adverse prognostic outcome." (PMID 39654885, 2024).
DHDH also shares sentences with these, for which no sentence is quoted: Hypertension (1 paper); infection (1); Obesity (1).